IL13RA2 (interleukin 13 receptor subunit alpha 2)
Diseases named in the same sentence as IL13RA2 in open-access papers (continued):
Sharing a sentence is not in itself a finding about the gene and the disease.
melanoma (36 papers, 2009 to 2025). A malignant, usually aggressive tumor composed of atypical, neoplastic melanocytes. "A promising antigen, interleukin-13 receptor alpha 2 (IL13Rα2), is overexpressed in melanoma and linked to tumor invasiveness and poor prognosis; IL13Rα2-targeted CAR T-cells are currently being studied in a Phase I clinical trial (NCT04119024)." (PMID 40940995, 2025). "Null mutations of TMEM219 or IL-13Rα2 also phenocopied one another as regards the ability of Chi3l1 to inhibit oxidant-induced apoptosis and lung injury, promote melanoma metastasis and stimulate TGF-β1." (PMID 27629921, 2016). "Recent studies by the Strober group also highlighted the importance of IL-13Rα2 in the progression of malignant melanoma, where its activation by IL-13 caused TGF-β1 elaboration, which inhibited tumor immune surveillance and favored tumor growth." (PMID 23972995, 2013). "In this context, we have demonstrated that prophylactic and therapeutic vaccination of immunocompetent mice with D5 melanoma with cDNA vaccine encoding human IL-13Rα2 caused significant antitumor response." (PMID 21067607, 2010). "A separate phase I clinical trial is currently underway studying CAR T-cells targeting IL13Ra2, a protein expressed in melanoma in 25% of patients." (PMID 40004731, 2025). "Several studies have reported that pulmonary melanoma metastasis is primarily mediated by IL-13Rα2-dependent mechanisms involving TGF-β1 production in the lung." (PMID 40643503, 2025). "IL13RA2 is another gene whose overexpression has been identified in melanoma and other cancer types, and it likely plays a pro-tumorigenic role in vivo." (PMID 36230844, 2022). "They demonstrated that overexpression of IL13Rα2 in patients with melanoma led to increased expression of amphiregulin, a component of the EGF family and a proangiogenic factor, resulting in the stimulation of angiogenesis and tumor growth." (PMID 36143291, 2022). "IL-13Rα2 is overexpressed in melanoma, renal cell carcinoma (RCC), adrenocortical carcinoma (ACC), and a variety of brain tumors." (PMID 35464460, 2022). "Although the role of IL13Rα2 in melanoma progression is likely attributed to its proangiogenic function, its roles in other aspects of melanoma progression such as metastasis need to be further characterised." (PMID 30718742, 2019). "Our results, taken together with the previous reports, suggest that the expression of IL13Rα2 enhances melanoma tumorigenesis in vivo via promoting angiogenesis through the expression of angiogenesis-triggering factors such as amphiregulin." (PMID 30718742, 2019). "Next we examined the frequency of IL13Rα2 expression in human melanoma samples by using tissue microarrays." (PMID 30718742, 2019). "We showed that IL13Rα2 in malignant melanoma promoted tumorigenicity by stimulating angiogenesis using gain-of-function and loss-of-function studies." (PMID 30718742, 2019). "IL13Rα2 stable transfectants, SK-IL13Rα2 cells, showed similar expression level of IL13Rα2 compared to that of A375 melanoma cells." (PMID 30718742, 2019). "We showed that IL13Rα2 expression not only enhanced the expression of amphiregulin but also suppressed in vitro proliferation of SK-MEL-28 cells, suggesting that IL13Rα2 transduces intracellular signals that regulated these events in melanoma cells." (PMID 30718742, 2019). "We also found that the expression of amphiregulin, a member of the epidermal growth factor (EGF) family, was correlated with IL13Rα2 expression in cultured melanoma cells, xenograft tumour tissues and melanoma clinical samples." (PMID 30718742, 2019). "We showed that expression of IL13Rα2 in the malignant melanoma SK-MEL-28 cells increased expression of angiogenic factor, amphiregulin as well as enhanced tumour angiogenesis and tumorigenicity in vivo." (PMID 30718742, 2019).
melanoma (continued). "While IL13Rα2 expression in human melanoma cells decreased their proliferation in vitro, it promoted in vivo tumour growth and angiogenesis in melanoma xenograft mouse model." (PMID 30718742, 2019). "On the other hand, our data showed that substantial expression of IL13Rα2 was observed in various human melanoma tissues including metastatic malignant melanoma from the armpit (lymph node), malignant melanoma from the thigh, cunnus, skin and right sole." (PMID 30718742, 2019). "In this study we investigated the expression of IL13Rα2 in malignant melanoma and its role in the progression of melanoma." (PMID 30718742, 2019). "Our data revealed that the expression of IL13Rα2, which was detected in a subgroup of human melanoma specimens, was correlated with the tumorigenicity of multiple types of melanoma cells." (PMID 30718742, 2019). "Because IL13Rα2 decreased the in vitro proliferation of melanoma cells, we next attempted to study the effect of IL13Rα2 expression on in vivo tumour growth of melanoma cells." (PMID 30718742, 2019). "In this study they used D5 murine melanoma cells transfected with human IL13Rα2 (D5 IL13Rα2) and inoculated the cells in two different locations." (PMID 30621280, 2019). "IL13RA2 was highly expressed in some melanoma cell lines, suggesting that IL13Rα2 is highly expressed in certain regions of melanoma." (PMID 30718742, 2019). "We generated 2 novel 2nd generation CARs targeting IL13RA2 based on humanized monoclonal antibodies, which recognized the IL13RA2-expressing melanoma cell lines A375 and A375BR." (PMID 30400835, 2018). "When considered in combination, these results demonstrate that endogenous CD44, similar to IL-13Rα2, plays a critical role in pulmonary melanoma metastasis and TGF-β1 production." (PMID 30165890, 2018). "Based on the observation of immunologically relevant expression of IL13RA2 mRNA in metastatic lesions of melanoma patients, we tested the potential of this cancer/testes antigen as a target for cellular immunotherapies." (PMID 30400835, 2018). "To further validate the specificity of [64Cu]Pep-1L in vivo, we produced a novel inducible hIL13RA2 expressing murine melanoma cell line that we demonstrated expresses IL13RA2 only after induction with doxycycline." (PMID 28881623, 2017). "Melanoma cell challenge also augmented and Poly(I:C) inhibited the expression of the Chi3l1 receptor IL-13Rα2." (PMID 27198666, 2016). "IL-13-PE has also been shown to work synergistically with paclitaxel in an immunodeficient animal model of HNSCC with gemcitabine for pancreatic cancer and a DNA vaccine of IL-13Rα2 in melanoma, breast, and sarcoma tumor models." (PMID 23421960, 2013). "Recent studies have demonstrated that pulmonary melanoma metastasis is mediated via an IL-13Rα2-dependent mechanism that requires the production of TGF-β1." (PMID 23972995, 2013). "We have previously demonstrated that splenocytes from C57BL/6 mice challenged with mouse melanoma (D5α2) when vaccinated with IL-13Rα2 DNA, mediated a significant lysis of target cells (38% lysis at E/T 50:1)." (PMID 21067607, 2010). "Importantly, enhanced IFNγ production and improved target cell killing by PD-1high CAR T cells was observed in human anti-IL-13 receptor α2 (IL13Rα2) CAR-T cells co-incubated with a human melanoma cell." (PMID 37388744, 2023). "CHI3L1 activates the IL‐13Rα2‐dependent activation of the AKT pathway in melanoma metastasis." (PMID 34758182, 2022). "For example, chitinase-3-like protein 1 (CHI3L1) could bind to IL-13Rα2 and regulate oxidant injury, apoptosis, and melanoma metastasis." (PMID 33450900, 2021). "Our finding revealing that IL13Rα2 expression was restricted to only a subset of melanoma cells prompted us to examine whether IL13Rα2 could regulate the oncogenic capacity of malignant melanoma." (PMID 30718742, 2019).
melanoma (continued). "However, detailed mechanisms how IL13Rα2 regulates the expression of amphiregulin and proliferation of melanoma cells need to be elucidated in the future." (PMID 30718742, 2019). "In accordance with the present in vitro and in vivo analyses in various melanoma cells, TCGA analysis showed that IL13RA2 expression was correlated with AREG expression in malignant melanoma patients, suggesting that IL13Rα2 regulated amphiregulin expression in human melanoma patients." (PMID 30718742, 2019). "The present study indicated that IL13Rα2 expression in melanoma cells enhanced tumour angiogenesis." (PMID 30718742, 2019). "Thus in the present study, we studied the expression pattern of IL13Rα2 in malignant melanoma and elucidated the relationship between the expression of IL13Rα2 and tumour progression in melanoma." (PMID 30718742, 2019). "The present finding that IL13Rα2 is expressed in a subgroup of melanoma cells and promotes tumorigenesis suggest IL13Rα2 to be a promising target for the development of novel therapeutic strategy against melanoma." (PMID 30718742, 2019). "In the present study, we showed that IL13Rα2 was expressed in approximately 7.5% melanoma patients." (PMID 30718742, 2019). "However, the role of IL13Rα2 with respect to the pigmentation in the pathogenesis and progression of melanoma should be elucidated in the future." (PMID 30718742, 2019). "Although IL13Rα2 is implicated in the progression of various types of cancer, its expression and roles in the malignant melanoma have not yet been elucidated." (PMID 30718742, 2019). "In order to study whether IL13Rα2-dependent tumour growth was mediated by enhanced angiogenesis, we investigated whether altered expression of IL13Rα2 would affect new vessel formation in melanoma tumour tissues." (PMID 30718742, 2019). "The PECAM-1-positive vascular area in the tumour tissue derived from the SK-IL13Rα2 cells was significantly larger when compared with the tumour derived from the SK-MEL-28 cells, implying that the expression of IL13Rα2 in malignant melanoma enhanced angiogenesis." (PMID 30718742, 2019). "In addition to brain cancer, IL13RA2 has also been reported to be highly expressed in other deadly malignancies, including melanoma, head and neck, ovarian and pancreatic cancers." (PMID 28881623, 2017). "Furthermore, we produced a novel inducible human (h) IL13RA2-expressing melanoma tumor model to demonstrate specificity of Pep-1L to IL13RA2." (PMID 28881623, 2017). "We also found evidence that regulating NKT cells could be involved in the immune response against B16F10-Nex2 melanoma in the mouse by the protective effect exerted by the neutralization of IL-13 using an IL-13Rα2-Fc chimera, enhanced by IL-12." (PMID 19968878, 2009). "In addition, in order to investigate whether the increased expression of amphiregulin in melanoma cells is cell-autonomously regulated by IL13Rα2, we studied the amphiregulin expression in various melanoma cells in which IL13Rα2 expression was altered." (PMID 30718742, 2019). "Therefore, we hypothesised that IL13Rα2 in malignant melanoma would stimulate the secretion of angiogenesis-inducing factors." (PMID 30718742, 2019). "The loss of IL13Rα2 expression in the A375 melanoma cells did not alter the VEGF expression." (PMID 30718742, 2019). "The CHI3L1/IL‐13Rα2 complex accompanied by TMEM219 promotes oxidant‐induced apoptosis, lung injury, and melanoma metastasis through activation of the macrophage ERK/AKT pathway." (PMID 34758182, 2022). "Regardless, IL-13Rα2-targeted CAR T cells are under investigation in six clinical trials in primary CNS malignancies and one in melanoma (clinicaltrials.gov)." (PMID 35464460, 2022). "In order to study the effect of IL13Rα2 expression on the proliferation of malignant melanoma cells, the SK-MEL-28 cells and SK-IL13Rα2 cells were allowed to grow for 5 days and the number of cells was determined in vitro." (PMID 30718742, 2019).
melanoma (continued). "IL13RA2 is especially attractive due to its ubiquitous expression on GBM, melanoma and other cancers." (PMID 28881623, 2017). "Therefore, in this work we used translational PET imaging to demonstrate the in vivo targeting of Pep-1L, a peptide reported to target IL13RA2, an attractive tumor-associated biomarker that we and others have demonstrated to be present on a number of deadly malignancies, including GBM and melanoma." (PMID 28881623, 2017). "Prior studies from our laboratory and the present investigations demonstrate that IL-13Rα2 and TMEM219 play critical roles in melanoma metastasis." (PMID 27629921, 2016). "Here, the authors show that TMEM219 is a IL-13Rα2 co-receptor and modulates oxidant-induced apoptosis and lung injury, melanoma metastasis and TGF-β1 signalling, downstream of Chi3l1-IL-13Rα2." (PMID 27629921, 2016). "The present studies demonstrate that mice that lack IL-13Rα2 or TMEM219 manifest similar increases in IgE production and Th2 cytokine elaboration and similar decreases in MAPK and Akt signalling and melanoma metastasis." (PMID 27629921, 2016). "To accomplish this, we compared the B16-F10 melanoma cell-induced metastasis and TGF-β1 elaboration in WT mice, YKL-40 Tg mice, and IL-13Rα2 null mice." (PMID 23972995, 2013). "In order to address this issue, we used malignant melanoma SK-MEL-28 cells which show no detectable expression of IL13Rα2." (PMID 30718742, 2019). "No obvious correlation was observed between expression of IL13Rα2 and pigmentation in the melanoma cells used in the present study." (PMID 30718742, 2019). "To further demonstrate specificity of Pep-1L towards IL13RA2 in vivo, we exploited an IL13RA2-inducible melanoma tumor model that does not express receptor at baseline but expresses abundant receptor after treatment with doxycycline." (PMID 28881623, 2017). "B16F10 murine melanoma cells, which do not endogenously express IL13RA2, were transfected with a tetracycline inducible plasmid expressing both mCherry and hIL13RA2." (PMID 28881623, 2017). "Thus, Poly(I:C) inhibits melanoma metastasis, Chi3l1/BRP-39 accumulation and IL-13Rα2 expression via the RLH innate immune pathway and TLR3 does not play a major role in these responses." (PMID 27198666, 2016). "Lastly, they demonstrate that YKL-40 activates MAPK, Akt, and Wnt/β-catenin signaling pathways and regulates apoptosis, pyroptosis, inflammasome activation, oxidant injury, antibacterial responses, melanoma metastasis, and TGF-β1 elaboration via IL-13Rα2-dependent mechanisms." (PMID 23972995, 2013). "Specifically, they characterize the first receptor for any GH 18 moiety by demonstrating that the chitinase-like protein (CLP) Chi3l1 binds to, signals, and regulates oxidant injury, apoptosis, pyroptosis, inflammasome activation, pathogen responses, melanoma metastasis, and TGF-β1 via IL-13Rα2." (PMID 23972995, 2013). "We also tested prophylactic vaccination in D5 melanoma tumor transfected with human IL-13Rα2 as D5 did not express IL-13Rα2." (PMID 21067607, 2010). "Importantly, none of the CAR-Ts displayed any cytotoxicity nor secreted IFN-γ in response to IL13Rα2-negative Mel526 melanoma cells." (PMID 37563127, 2023). "However, IL13Rα2 induced a minimal increase in the VEGF level, and moreover, loss of IL13Rα2 expression in the A375 melanoma cells did not change the level of VEGF." (PMID 36143291, 2022). "Furthermore, in order to determine whether IL13RA2 expression level in melanoma clinical samples was correlated with AREG expression, we analysed IL13RA2 and AREG expression by using the TCGA (The Cancer Genome Atlas) database." (PMID 30718742, 2019). "Increased expression of IL13Rα2 in A2058 and SK-MEL-28 melanoma cells, which do not express endogenous IL13Rα2, the expression of amphiregulin was upregulated." (PMID 30718742, 2019).
brain tumors (33 papers, 2013 to 2025). "Many other studies (e.g)., reporting a correlation between high IL13RA2 levels and poor prognosis in primary brain tumors also use gene expression data." (PMID 40663259, 2025). "CAR-M therapies directed against HER2 and EGFRvIII improved survival in preclinical models and are anticipated to cross the blood–brain barrier, while IL-13Rα2 and mesothelin have been validated as potential targets for brain tumor eradication." (PMID 41417432, 2025). "CAR-Ms targeting tumor-specific antigens such as EGFRvIII, IL-13Rα2, and mesothelin have also demonstrated considerable potential for treating brain tumors." (PMID 41417432, 2025). "To our knowledge, we report the largest CAR-T clinical trial in brain tumors, assessing the feasibility, safety and bioactivity of IL-13Rα2-CAR-T cells in rGBM and other HGGs." (PMID 38454126, 2024). "The cerebrospinal fluid of brain tumor patients also showed higher levels of Interleukin 13 Receptor alpha 2 (IL13Rα2) when quantified using flow cytometry." (PMID 39001524, 2024). "To test this, we established brain tumor xenografts using ffLuc-expressing PBT030-2, treated the mice intracranially with the IL13Rα2-CAR T cell variants, and then followed tumor size over time using biophotonic imaging." (PMID 36968221, 2023). "CAR T cells after lymphodepletion for the treatment of IL13Rα2 positive recurrent or refractory brain tumors in children are under clinical evaluation." (PMID 36721153, 2023). "IL-13Rα2 has long been recognized as a prognostic biomarker for poor disease prognosis in brain tumors including HGG." (PMID 35631512, 2022). "Recent studies suggest that overexpression of IL-13Rα2 is detected in up to 83% of malignant pediatric brain tumors, including DMG, and up to 78% of adult GBM." (PMID 35631512, 2022). "We evaluated the in vivo antitumor efficacy of the CAR T cells in our previously established xenograft brain tumor model with IL13Rα2-expressing PBT030-2 cells engineered to express the firefly luciferase (ffLuc) reporter gene." (PMID 35939683, 2022). "To expand on these observations, we performed additional in vitro tumor killing and cytokine release assays using a panel of patient-derived brain tumor cell lines engineered to express different levels of IL13Rα2." (PMID 35939683, 2022). "The glioma-associated antigen interleukin-13 receptor alpha 2 (IL13Rα2), found in approximately 58% of adult GBM cases and 83% of pediatric brain tumors, has also been targeted by CAR-T cells in the clinical setting." (PMID 33496872, 2021). "IL13RA2 is overexpressed in the majority of high-grade astrocytomas and other tumors, such as renal cell carcinoma, brain tumor, and ovarian cancer." (PMID 31607839, 2019). "Targeting IL13Rα2 is currently the focus of ongoing clinical development for the treatment of brain tumors." (PMID 24787244, 2014). "The IL13RA2 gene is often overexpressed in brain tumors and is involved in the invasion and metastasis of ovarian cancer cells." (PMID 25481245, 2014). "Our group has developed a therapeutic platform to target IL13Rα2-positive brain tumors by engineering human cytotoxic T lymphocytes (CTLs) to express the IL13-zetakine chimeric antigen receptor." (PMID 24787244, 2014). "Our novel antibodies detected IL-13RA2 in a variety of human and canine brain tumors and cell lines on western blots, defining an extended spectrum of potential target tumors beyond the high grade astrocytomas previously reported." (PMID 24147065, 2013). "Immunotherapy strategies targeting IL13Rα2 for brain tumors are being clinically pursued based on its selective expression on malignant versus normal brain tissue." (PMID 24204956, 2013). "We have taken a bioinformatics approach towards understanding the biological context of IL-13 receptor α2 (IL13Rα2) expression in brain tumors, and its functional significance for patient survival." (PMID 24204956, 2013).